RN7SKP62 (RN7SK pseudogene 62)
Gene: Miscellaneous RNA gene on chromosome 5 (100,733,058 to 100,733,386, forward strand). Ensembl gene ENSG00000207269.
Homologues: Orthologues: chimpanzee 7SK (99% identical). Paralogues in human: 7SK (87% identical), RN7SKP174 (81% identical), RN7SKP185 (80% identical), RN7SKP118 (79% identical), RN7SKP187 (79% identical), RN7SKP48 (79% identical), RN7SKP178 (78% identical), RN7SKP227 (78% identical), RN7SKP76 (76% identical), RN7SKP55 (75% identical), RN7SKP292 (75% identical), RN7SKP104 (72% identical), and 284 more.